LILRB2 (leukocyte immunoglobulin like receptor B2)
Description:
Receptor for class I MHC antigens. Recognizes a broad spectrum of HLA-A, HLA-B, HLA-C, HLA-G and HLA-F alleles. Involved in the down-regulation of the immune response and the development of tolerance. Recognizes HLA-G in complex with B2M/beta-2 microglobulin and a nonamer self-peptide (peptide-bound HLA-G-B2M) triggering differentiation of type 1 regulatory T cells and myeloid-derived suppressor cells, both of which actively maintain maternal-fetal tolerance. Competes with CD8A for binding to class I MHC antigens. Inhibits FCGR1A-mediated phosphorylation of cellular proteins and mobilization of intracellular calcium ions.
Synonyms: LIR-2; ILT-4; MIR-10; CD85d; ILT4; LIR2; MIR10
Tractability: Small molecule: a structure with a bound ligand is known. Antibody: UniProt places it where antibodies can reach, with high confidence; its Gene Ontology location is reachable by antibodies, with high confidence; UniProt predicts a signal peptide or a membrane-spanning region. PROTAC: its protein half-life has been measured.
Gene: Protein-coding gene on chromosome 19 (54,273,812 to 54,281,184, reverse strand). Ensembl gene ENSG00000131042.
Subcellular location: Cell membrane
Pathways (Reactome):
Immune System: Immunoregulatory interactions between a Lymphoid and a non-Lymphoid cell; Neutrophil degranulation
Gene Ontology:
Molecular function: amyloid-beta binding; cell adhesion molecule binding; inhibitory MHC class I receptor activity; MHC class I protein binding; MHC class Ib protein binding; MHC class Ib protein complex binding; protein binding; protein homodimerization activity; protein phosphatase 1 binding; protein-containing complex binding
Biological process: cellular response to lipopolysaccharide; Fc receptor mediated inhibitory signaling pathway; heterotypic cell-cell adhesion; immune response-inhibiting cell surface receptor signaling pathway; interleukin-10-mediated signaling pathway; negative regulation of antigen processing and presentation; negative regulation of calcium ion transport; negative regulation of T cell costimulation; negative regulation of T cell proliferation; positive regulation of regulatory T cell differentiation; positive regulation of T cell proliferation; positive regulation of T cell tolerance induction; positive regulation of tolerance induction; signal transduction; cell surface receptor signaling pathway; cell-cell signaling; cellular defense response; immune response; learning or memory; negative regulation of postsynaptic density organization; negative regulation of protein metabolic process; positive regulation of interleukin-6 production; positive regulation of long-term synaptic depression; regulation of dendritic cell differentiation; regulation of long-term synaptic potentiation
Cellular component: cell surface; cytoplasm; extracellular region; plasma membrane; ficolin-1-rich granule membrane; membrane; tertiary granule membrane
Genetic constraint (gnomAD): Loss-of-function variants: 47 observed, 69.42 expected, observed/expected ratio (o/e) 0.68, 90% interval 0.54 to 0.86. The upper end of that interval is the gene's LOEUF score, 0.86, which puts it in group 3 of 6, group 1 being the genes least tolerant of losing a copy. Missense variants: 767 observed, 727.72 expected, observed/expected ratio (o/e) 1.05, 90% interval 0.99 to 1.12. Synonymous variants: 279 observed, 295.04 expected, observed/expected ratio (o/e) 0.95, 90% interval 0.86 to 1.04.
Homologues: Orthologues: macaque LILRB1 (82% identical), macaque LILRA2 (60% identical), macaque LILRA1 (59% identical), rat Pirb (47% identical), rat Lilrb3 (42% identical), mouse Pira12 (39% identical), mouse Pirb (39% identical), mouse Pira2 (38% identical), mouse Pira1 (38% identical), mouse Pira13 (38% identical), mouse Lilra6 (37% identical), rat LOC134485274 (37% identical), and 4 more. Paralogues in human: LILRB1 (85% identical), LILRB3 (67% identical), LILRB5 (67% identical), LILRA1 (63% identical), LILRA2 (60% identical), LILRA6 (52% identical), LILRA4 (49% identical), LILRB4 (41% identical), KIR3DL1 (27% identical), KIR3DL2 (27% identical), KIR3DL3 (25% identical), LILRA5 (23% identical), and 13 more.
Diseases named in the same sentence as LILRB2 in open-access papers:
LILRB2 is named in the same sentence as 99 diseases in open-access papers, as found by Europe PMC text mining. Sharing a sentence is not in itself a finding about the gene and the disease. The quoted sentences say what the papers report.
non-small cell lung carcinoma (16 papers, 2015 to 2025). A group of at least three distinct histological types of lung cancer, including non-small cell squamous cell carcinoma, adenocarcinoma, and large cell carcinoma. "describe the expression on non-small-cell lung carcinoma (NSCLC) and show the correlation between high LILRB2 expression and reduced infiltration of lymphoid cells in the tumor tissue." (PMID 34276685, 2021). "Herein, we determined that both LILRB2 and its soluble ligand ANGPTL2 are highly expressed in non-small cell lung cancer (NSCLC) samples, and levels are adversely related to patient prognosis." (PMID 26056041, 2015).
lung carcinoma (9 papers, 2015 to 2025). "A study pointed out that LILRB2 was a receptor of natural killer (NK) cell and was associated with lung cancer cell." (PMID 29069717, 2017). "A recent study showed that LILRB2 was expressed in lung cancer tissues and that its expression resulted in poor patient OS." (PMID 35321724, 2022). "In contrast, some studies have also shown that LILRB2 regulates tumor cell proliferation, invasion, and migration and promotes tumor progression in lung cancer." (PMID 35321724, 2022). "To examine the expression of LILRB2 in human lung cancer cell lines, we first evaluated LILRB2 expression on several NSCLC cell lines, including H1299, A549, H460, and H292G cells, by flow cytometry." (PMID 26056041, 2015). "We further examined the expression of LILRB2 in primary tissues collected from lung cancer patients." (PMID 26056041, 2015). "Our results suggest that signaling involving ANGPTL2 and LILRB2 is important for lung cancer development and represents a novel target for treatment of this type of cancer." (PMID 26056041, 2015). "In this study, we provide evidence that both ANGPTL2 and LILRB2 are often expressed in lung cancer tissue and play important roles in the proliferation and survival of cancer cells." (PMID 26056041, 2015). "LILRB2 was proposed as a key player in the signaling pathway of lung cancer development." (PMID 31671645, 2019). "CaMK1 appears to be tightly controlled by LILRB2/SHP2 signaling in lung cancer cells." (PMID 26056041, 2015). "Mechanistic analyses indicated that ANGPTL2 binds LILRB2 to support the growth of lung cancer cells and that the SHP2/CaMK1/CREB axis controls the proliferation of lung cancer cell lines." (PMID 26056041, 2015).
acute myeloid leukemia (7 papers, 2015 to 2025). Acute myeloid leukemia (AML) is a group of neoplasms arising from precursor cells committed to the myeloid cell-line differentiation. "High let-7a-2-3p expression was associated with reduced expression of oncogene JDP2 and leukocyte immunoglobulin-like receptor (LILRA5/6, LILRB2/3), which are correlated with poor prognosis in cytogenetically normal acute myeloid leukemia (CN-AML) patients." (PMID 27179712, 2016). "In acute myeloid leukemia (AML), LILRB2 is upregulated on leukemic stem cells and immunosuppressive myeloid cells." (PMID 40821795, 2025). "LILRB2 and PirB are expressed by hematopoietic stem cells (HSCs) and leukemia stem cells in humans and mice, respectively, and support the ex vivo expansion of HSCs and acute myeloid leukemia (AML) development." (PMID 29482582, 2018). "Recently we demonstrated that leukocyte immunoglobulin-like receptor subfamily B member 2 (LILRB2) and its murine homolog, paired immunoglobulin-like receptor B (PIRB), are expressed on hematopoietic stem cells and acute myeloid leukemia stem cells and function in maintenance of stemness." (PMID 26056041, 2015).
breast carcinoma (7 papers, 2014 to 2025). "Elevated levels of IL-10 in LILRB2+ breast cancer tissue positively correlates with advanced disease and lymph node metastasis, as well as reduction in tumour-infiltrating lymphocytes (TIL)." (PMID 38022598, 2023). "Additionally, LILRB2 is found on stromal macrophages, fibroblasts and plasma cells within the TME of primary breast cancer patients." (PMID 38022598, 2023).
Alzheimer disease (6 papers, 2015 to 2022). A progressive, neurodegenerative disease characterized by loss of function and death of nerve cells in several areas of the brain leading to loss of cognitive function such as memory and language. "The LILRB2 gene is an inhibitory receptor gene of HLA Class I, and it was found that the LILRB2 gene encodes a neuronal cell-surface receptor that is associated with occurrences of Alzheimer disease as a receptor for β-amyloid." (PMID 35741860, 2022). "In Alzheimer’s disease, soluble β-amyloid (Aβ) oligomers were known to lead to synaptic loss associated with AD, And human LILRB2 was a β-amyloid receptor, so blocking the function of LILRB2 is a potential therapeutic target for AD." (PMID 35938019, 2022). "However, LILRB2 was recently identified as a risk gene contributing to Late-onset Alzheimer’s disease (LOAD) in a large genome-wide association study involving over 1 million patients’ data." (PMID 35717259, 2022). "The inhibition of the binding of β-amyloid to LilrB2 has become a potential pathway for the treatment of Alzheimer disease." (PMID 35741860, 2022). "Using a recently published single-cell RNA-seq database for Alzheimer’s disease, we found that LILRB2 was upregulated in human AD patient microglia by 4.5-fold over healthy control." (PMID 35717259, 2022). "Human LILRB2 and its murine ortholog PirB interact with soluble β-amyloid, leading to enhanced cofilin signaling, which is observed in the brains of humans with Alzheimer’s disease." (PMID 34737739, 2021). "It is postulated that due to the orthologous relationship between LILRB2 and PirB, LILRB2 may contribute to Alzheimer’s disease neuropathology, and might be a suitable therapeutic target." (PMID 34737739, 2021).
colorectal cancer (6 papers, 2020 to 2025). A primary or metastatic malignant neoplasm that affects the colon or rectum. "Interestingly, in colorectal cancer it has been recently described that tumour-derived LILRB2 promotes tumour growth by increasing angiogenesis, and its blocking sensitises tumours to bevacizumab (anti-VEGF-A) treatment." (PMID 38022598, 2023).
leukemia (6 papers, 2015 to 2025). A malignant (clonal) hematologic disorder, involving hematopoietic stem cells and characterized by the presence of primitive or atypical myeloid or lymphoid cells in the bone marrow and the blood. "Gene expression profile and experimental validation of CD10+CD19+ precursor B lymphoblasts in pediatric ALL revealed significant LILRB2 downregulation in leukemia cells." (PMID 40860159, 2025). "We showed that LILRB2 was the receptor for ANGPTL2 to sustain the stemness of HSCs and leukemia stem cells." (PMID 36855057, 2023). "Our previous study indicated that an inhibitory immune receptor, leukocyte immunoglobulin-like receptor subfamily B member 2 (LILRB2), is critical for LIC maintenance and leukemia development." (PMID 27855694, 2016). "We found that binding of Angptls to PirB/LILRB2 induces activation of tyrosine phosphatase SHP-1/SHP-2 and calcium/calmodulin-dependent protein kinase CAMKIV, both known to be critical for HSC repopulation and stimulation of leukemia development." (PMID 29482582, 2018).
clear cell renal cell carcinoma (5 papers, 2020 to 2025). "LILRA1, LILRA2, LILRA5, LILRB1, LILRB2, and LILRB3 are differentially expressed across several cancer types, including lung squamous cell carcinoma, lung adenocarcinoma, papillary renal cell carcinoma, and clear cell renal cell carcinoma, suggesting a potential pan-cancer role for LILR family genes." (PMID 40843931, 2025).
endometriosis (5 papers, 2018 to 2023). The growth of functional endometrial tissue in anatomic sites outside the uterine body. "The AA genotypes of the rs41308748 polymorphism of the LILRB1 gene and AG rs383369 of the LILRB2 gene predisposed to endometriosis and its progression." (PMID 34638893, 2021). "The AA genotypes of rs41308748 polymorphism of the LILRB1 gene and the AG genotypes of rs383369 polymorphism of the LILRB2 gene predisposed to endometriosis and its progression." (PMID 33153202, 2020). "LILRB2 is involved in macrophage maturation and pro-inflammatory phenotypes, and the rs383369 SNP in a homozygous state was associated with lesser severity in inflammatory endometriosis, as well as in cancer response to therapy." (PMID 37686397, 2023). "The study of Polish scientists analyzed whether polymorphisms of HLA-G, KIR2DL4, LILRB1 and LILRB2 genes may affect susceptibility to endometriosis and disease progression." (PMID 34638893, 2021). "In this study we investigated whether HLA-G, KIR2DL4, LILRB1 and LILRB2 polymorphisms may influence susceptibility to endometriosis and disease progression." (PMID 29234882, 2018). "Binding of human leukocyte antigen (HLA) G to its receptors LILRB1 and LILRB2 on NK cells is important in the pathogenesis of endometriosis." (PMID 35628346, 2022). "Certain polymorphisms of HLA-G protected against endometriosis, and polymorphisms of LILRB1 and LILRB2 were associated with susceptibility to endometriosis and its progression." (PMID 35628346, 2022). "In the present study we found that susceptibility to and the severity of endometriosis are associated with polymorphisms in the HLA-G, LILRB1 and LILRB2 genes." (PMID 29234882, 2018). "LILRB2 rs383369:AG genotype was almost five times more frequent in severe stages (III + IV) of endometriosis than in milder (I + II) stages (P = 0.043, Pcorr. = 0.215, OR = 7.02, 95% CI = 0.90–54.43)." (PMID 29234882, 2018). "The most important conclusion was that HLA-G and the receptors LILRB1 and LILRB2 may play a crucial role in eliminating endometriotic cells and the development of endometriosis." (PMID 35628346, 2022). "The putative role of HLA-G in the etiopathogenesis of endometriosis may be strengthened by our further observation that the disease is also associated with polymorphism in LILRB1 and LILRB2 genes coding for HLA-G receptors." (PMID 29234882, 2018). "Our results suggesting an association of LILRB2 rs383369-A with the absence of alloimmunisation appear to be consistent with previous results showing an association between this SNP in a homozygous state and lesser severity in inflammatory endometriosis, but this needs to be further investigated." (PMID 37686397, 2023).
HIV-1 infection (5 papers, 2012 to 2022). The type species of lentivirus and the etiologic agent of acquired immunodeficiency syndrome (AIDS). "Based on the work presented herein, we propose that variation in binding properties of HLA-B to the inhibitory myelomonocytic receptor LILRB2 can contribute to the overall HLA effects on HIV-1 infection outcomes." (PMID 24603468, 2014). "A study on LILRB2-HLA class I molecules verified that different binding levels between these molecules can result in different immune response outcomes and that a weak level of binding correlates with control of HIV-1 infection in a large cohort." (PMID 35877415, 2022). "In addition, a strong LILRB2-HLA-B*35-Px interaction is suggested to impair dendritic cell (DC) function during HIV-1 infection, possibly leading to faster disease progression." (PMID 24603468, 2014). "We used previously characterized HLA allotype-specific binding capacities of LILRB1 and LILRB2 as well as data from a large cohort of HIV-1-infected individuals (N = 5126) to test whether LILR-HLA class I interactions influence viral load in HIV-1 infection." (PMID 24603468, 2014). "Generally, LILRB2 is highly upregulated on DC during chronic progressive HIV-1 infection and seems to play an important role for inducing a tolerogenic profile of dendritic cells in the setting of immune tolerance after solid organ transplantation and during pregnancy." (PMID 22289474, 2012).
COVID-19 (4 papers, 2021 to 2024). A disease caused by infection with severe acute respiratory syndrome coronavirus 2. "Seven common key genes were found in these four hub gene sets, including FCER1G, ITGAM, LCP2, LILRB2, MNDA, SPI1, and TYROBP, which were considered core targets of IC and COVID-19." (PMID 38267482, 2024). "First, we compared the expression levels of five genes in COVID-19 and controls, finding that the expression of BIRC5, DTL, and NDC80 increased in COVID-19 while DNAJC4 and LILRB2 decreased." (PMID 37426635, 2023).
glioma (4 papers, 2021 to 2025). A benign or malignant brain and spinal cord tumor that arises from glial cells (astrocytes, oligodendrocytes, ependymal cells). "Moreover, PAX3 expression demonstrates significant positive correlations with multiple immune checkpoints, particularly PDCD1, SIGLEC7, and LILRB2, underscoring its involvement in immune regulation within the glioma microenvironment." (PMID 41180518, 2025). "We also observed positive correlations between the risk score and several immune checkpoint genes, including SIGLEC7, PDCD1, LILRB2, HAVCR2, and LAG3, which have been tied to poor prognosis in glioma." (PMID 41180518, 2025). "Higher expression of LILRB2 indicated shorter DFS and OS both in GBM patients and high-grade glioma patients, demonstrating that LILRB2 is an oncogene that indicates a dismal prognosis in GBM patients." (PMID 36853330, 2023). "Multivariate Cox analysis revealed that genes such as PILRA, LILRB2, and BATF were independent prognostic factors for glioma patients." (PMID 34540893, 2021).
hepatocellular carcinoma (4 papers, 2020 to 2025). A malignant tumor that arises from hepatocytes. "In hepatocellular carcinoma (HCC), LILRB1/LILRB2 suppress cytokine production by liver-infiltrating myeloid cells." (PMID 40821795, 2025).
lymph node metastasis (4 papers, 2014 to 2025). "Univariate Cox analysis revealed that expression levels of LILRB2 and APE1, TNM stage, and lymph node metastasis (LNM) were associated with CRC prognosis." (PMID 41383852, 2025). "Moreover, LILRB2 expression is markedly upregulated in CRC, where its elevation correlates with unfavorable clinicopathological parameters, including poor-to-moderate differentiation, lymph node metastasis (LNM), advanced TNM stage, and poor prognosis." (PMID 41383852, 2025).